STAT3 (signal transducer and activator of transcription 3)
Diseases named in the same sentence as STAT3 in open-access papers (continued):
Sharing a sentence is not in itself a finding about the gene and the disease.
bladder cancer (continued). "Recently, it has been noted that EGFR signalling promotes progression of T24 bladder carcinoma cells via STAT3 upregulation of transcription, including that of matrix metaloproteinases." (PMID 16804520, 2006). "Persistent STAT3 signaling has been observed in numerous malignancies, and growing preclinical evidence underscores the effectiveness of targeting STAT3 in the treatment of various cancers, including bladder cancer." (PMID 39997178, 2025). "To further confirm whether CAFs regulate bladder cancer cell chemoresistance through CCR7 induced STAT3 activation, we employed CAFs infected with shNC or shCXCL14." (PMID 40898244, 2025). "A study on the STAT3 inhibitor WP1066 demonstrated that when administered at varying doses to bladder cancer cells, WP1066 could block STAT3 phosphorylation, reduce cancer cell survival and proliferation, and induce apoptosis." (PMID 40635786, 2025). "Inhibitors targeting STAT3/5 have demonstrated antitumor activity in bladder cancer models." (PMID 40277814, 2025). "Thus, our current findings underpin STAT3 blockage as a potential strategy for bladder cancer treatment." (PMID 39997178, 2025). "In this context, both APE1 and STAT3 proteins have been listed as possible targets, and the combined inhibition of these proteins led to a decrease in cancer cell survival in pancreatic and bladder cancer." (PMID 41090323, 2025). "CCL5 is believed to promote the proliferation and metastasis of bladder cancer through the JAK2/STAT3 signaling pathway, which might suggest the reliability of finasteride in reducing the occurrence of BCa from the perspective of the immune microenvironment." (PMID 39944628, 2025). "This study provides the first evidence that EV is associated with increased PD-L1 expression, along with upregulation of NF-κB and STAT3, suggesting a mechanistic link that may contribute to immune modulation in nectin-4-high bladder cancer cells." (PMID 40999385, 2025). "Research has demonstrated that inflammatory cytokines (e.g., IL-6, TNF-α) can inhibit erythrocyte maturation, leading to increased RDW, while simultaneously activating oncogenic pathways such as STAT3, promoting tumorigenesis, immune evasion, and driving bladder cancer progression." (PMID 41561745, 2025). "Although miR-145 is typically considered a tumor suppressor, it may assume a pro-metastatic role in metastatic bladder cancer by modulating signaling pathways such as STAT3." (PMID 40689207, 2025). "Experimental results suggest that EZH2 may promote the proliferation and migration of bladder cancer cells through the STAT3 pathway, highlighting its potential role in bladder cancer progression." (PMID 40635786, 2025). "Furthermore, multiple in vitro and preclinical studies have demonstrated the therapeutic benefits of pharmacologically blocking STAT3 to treat bladder cancer." (PMID 39997178, 2025). "A recent study in bladder cancer showed that SMARCB1-deficient tumours displayed increased IL6–janus kinase–signal transducer and activator of transcription 3 (IL6-JAK-STAT3) signalling in in vivo models and patient tumours, believed to be associated with metastasis." (PMID 40422882, 2025). "EV is associated with increased PD-L1 expression, along with upregulation of NF-κB and STAT3, suggesting a mechanistic link that may contribute to immune modulation in nectin-4-high bladder cancer cells." (PMID 40999385, 2025). "Furthermore, Pae not only induces apoptosis in cancer cells but also inhibits the nuclear translocation of STAT3 in bladder cancer cells, thereby suppressing the proliferation of human BCa cell lines in a concentration- and time-dependent manner." (PMID 40635786, 2025). "The potential relationship between the interference of CENPW expression and the inhibition of bladder cancer may be attributed to the inactivation of STAT3." (PMID 38213721, 2024). "GSDMB also promotes bladder carcinoma progression by activating the STAT3 pathway." (PMID 38711020, 2024).
bladder cancer (continued). "Based on these results, we may speculate that loss-of-expression in SPOP might also stabilize PD-L1 protein in bladder cancer cells and induce immune escape via TAMs, beyond the STAT3/CCL2/IL-6 axis." (PMID 39479456, 2024). "In addition, artesunate (ART, a STAT3 inhibitor) showed a synergistic effect with RC48 against basal bladder cancer both in vitro and in vivo." (PMID 39840049, 2024). "We found the recurrent high enrichment score of the JAK/STAT3 pathway in basal bladder cancer." (PMID 39840049, 2024). "USP24 interacts with GSDMB and acts as a deubiquitinating enzyme (Dub) to remove polyubiquitin chains from GSDMB,304 increasing the stability of GSDMB in bladder cancer and further promoting downstream phosphorylation of STAT3, which promotes bladder cancer cell proliferation." (PMID 38584157, 2024). "Subsequently, we examined whether the mTOR and STAT3 double knockdown would prove more advantageous than single gene knockdowns of each gene as a therapeutic strategy in bladder cancer." (PMID 38886756, 2024). "Our initial target gene pair, mTOR and STAT3, is highly significant in bladder cancer." (PMID 38886756, 2024). "To further determine whether the JAK/STAT3 pathway occurred as a compensatory activation based on the downregulation of ERBB2 in basal bladder cancer, we performed RNA-sequencing to explore this speculation." (PMID 39840049, 2024). "Therefore, we suggest that knockdown of CENPW inhibits bladder cancer probably by repressing phosphorylation of STAT3." (PMID 38213721, 2024). "Notably, pharmacological inhibition of STAT3 has been proved to sabotage bladder cancer progression in murine model, therefore highlighting STAT3 as a promising target for the development of bladder cancer therapeutics." (PMID 37511611, 2023). "Consequently, stabilized GSDMB has been shown to modulate glucose metabolism by enhancing signal transducer and activator of transcription 3 (STAT3) phosphorylation in bladder cancer cells." (PMID 38066523, 2023). "Accordingly, it would be interesting to evaluate whether pharmacological inhibition of 5-HT6 leads to the blockade of STAT3 signaling and the resultant induction of apoptosis in human bladder cancer cells." (PMID 37511611, 2023). "Given the data above revealed sertindole as an inhibitor of STAT3 activation, either inherent in cells or induced by IL-6, we then asked whether sertindole-induced bladder cancer cytotoxicity was compromised if STAT3 remains active in sertindole-treated cells." (PMID 37511611, 2023). "Tumor tissues from clinical bladder cancer patients have exhibited significantly elevated expression of phosphorylated STAT3 compared with adjacent normal tissues, further confirming the oncogenic role of STAT3 in bladder cancer." (PMID 37511611, 2023). "β-AR plasmid suppressed p-STAT3 protein expression in bladder cancer cell." (PMID 37663229, 2023). "Mechanistically, sertindole inhibited the activation of signal transducer and activator of transcription 3 (STAT3), an oncogenic driver of bladder cancer, as sertindole lowered the levels of tyrosine 705-phosphorylated STAT3 along with that of STAT3′s target gene BCL-xL." (PMID 37511611, 2023). "Moreover, the IL-6/STAT3/PD-L1 pathway has been shown to be involved in the promotion of EMT in bladder cancer." (PMID 36230984, 2022). "It has been reported that phospho-STAT3 (p-STAT3) induces methylation of estrogen receptor 1 (ESR1) promoter in bladder cancer, and RacGAP1 induces phosphorylation of STAT3, which increases the expression of p-STAT3 and promotes its translocation into the nucleus to play a cancer-promoting role." (PMID 36227136, 2022). "Previous studies demonstrated that it could enact these functions through participating in the programmed death ligand-1/integrin β/activator of the transcription 3 (PD-L1/ITGB6/STAT3) signaling pathway in bladder cancer." (PMID 35893817, 2022).
bladder cancer (continued). "The proteomics and confirmation results demonstrated that PEPE2 treatment could increase PTP1B expression, and thus, the JAK/STAT3 pathway was inhibited in bladder cancer cells, implying that PTP1B might be a tumor suppressor protein in UBUC." (PMID 36362994, 2022). "STAT3 plays a significant role in bladder cancer metabolism." (PMID 36230984, 2022). "In preliminary studies, we found that the expression levels of the classic proto-oncogenes, IGF2BP1, MYC, LIN28B and STAT3 in bladder cancer T24 cells were higher than those in normal cells, while the expression levels of the tumor suppressor genes FTO and TIA1 were negligible in T24 cells." (PMID 35288535, 2022). "For example, STAT3 was a treatment target for bladder cancer therapy, and the anti-bladder cancer effects of berberine might involve disturbing the AK2-STAT3 signaling pathway via upregulation of miR-17-5p." (PMID 35889396, 2022). "Bladder cancer cells could also secrete exosomal miR-21 to promote cancer development by promoting activation of STAT3-induced M2 polarization." (PMID 39280890, 2022). "Moreover, we showed that survivin downregulation by HME due to STAT3 blockage contributes to HME-induced bladder cancer cytotoxicity." (PMID 36613579, 2022). "Thus, our discovery that HME is an inhibitor of STAT3 signaling implicates the translation potential of HME as a chemotherapeutic agent for bladder cancer." (PMID 36613579, 2022). "The results of this study showed that metformin could significantly enhance the antitumor effect of olaparib on bladder cancer cells, and these effects were mediated by downregulating STAT3/C-MYC signaling pathway proteins." (PMID 35783012, 2022). "Notably, preclinical evidence has validated STAT3 blockade as a promising therapeutic strategy for bladder cancer." (PMID 36613579, 2022). "RACGAP1 stimulates STAT3 phosphorylation and promotes its nuclear translocation, thus facilitating cell proliferation, migration, and decreased chemosensitivity to doxorubicin in bladder cancer." (PMID 35013128, 2022). "Notably, the present study first identified HME as a potent blocker for STAT3 signaling in bladder cancer cells, as HME markedly inhibited both constitutive and IL-6-inducible STAT3 activation." (PMID 36613579, 2022). "How HME suppresses STAT3 activation in bladder cancer cells was next addressed." (PMID 36613579, 2022). "Therefore, it can be assumed that STAT3 as a transcription factor has the function of activating PYCR1 in bladder cancer." (PMID 36227136, 2022). "Finally, RORC impairs STAT3 binding to STAT-3 mediated genes, leading to bladder cancer cells being sensitized to cisplatin." (PMID 36230984, 2022). "Previous research demonstrated that gasterminB could interact with STAT3 and activate STAT3 signalling, which promotes tumour cell growth in bladder cancer." (PMID 35233921, 2022). "Numerous research teams have inspected the role of STAT3 in bladder cancer." (PMID 36230984, 2022). "In conclusion, USP24 stabilizes GSDMB to promote STAT3 phosphorylation in bladder cancer cells." (PMID 34326684, 2021). "Furthermore, we demonstrated that GSDMB interacted with STAT3 to increase the phosphorylation of STAT3 and modulate the glucose metabolism and promote tumor growth in bladder cancer cells." (PMID 34326684, 2021). "Currently, the STAT3 inhibitors are being tested in clinical trials for bladder cancer." (PMID 33407095, 2021). "Furthermore, we used cryptotanshinone to inhibit the phosphorylation of Tyr 705 STAT3 in bladder cancer cells with knocking down or overexpressing GSDMB, resulting in constant protein and mRNA levels of HK2." (PMID 34326684, 2021). "In addition to the classical IL6/JAK/STAT3 pathway 11, other pathways participate in the activation of STAT3 in bladder cancer." (PMID 34326684, 2021). "Resveratrol decreased smoke induced EMT in bladder cancer via STAT3/Twist1 inhibition." (PMID 33572742, 2021).
bladder cancer (continued). "Furthermore, several proteins (e.g., EZH2 12 or Msi2 13), long non-coding RNA (e.g., SNHG16 14), and micro RNA (e.g., miR-98 14 or miR-4324) have been reported to be responsible for STAT3 activation in bladder cancer cells." (PMID 34326684, 2021). "We further showed that USP24 inhibitors could block this process via inducing GSDMB degradation in cancer cells, which provided a therapeutic strategy for inhibiting the GSDMB/STAT3 axis in bladder cancer." (PMID 34326684, 2021). "Also, ITGA2 expression and phosphorylation of AKT, STAT3, and p65 proteins in bladder cancer cells were greatly enhanced by silencing of lnc-STYK1-2 expression." (PMID 34332611, 2021). "In conclusion, GSDMB regulates IGFBP3 expression through the STAT3 pathway in bladder cancer." (PMID 34326684, 2021). "In addition, expression of FOXM1 as a prognostic factor in the survival of muscle invasive bladder cancer patients, STAT3 expression, and phosphorylation was identified to be substantially higher in basal-like bladder cancer." (PMID 35068946, 2021). "The results of the in vivo experiments were also completely consistent with these results, and no statistical difference in the tumor mass or volume was detected between the two groups, which further demonstrated that GSDMB promoted the progression of bladder cancer by regulating STAT3." (PMID 34326684, 2021). "Furthermore, STAT3 up-regulates LDHA expression to promote the proliferation of urinary bladder cancer cells." (PMID 34326684, 2021). "Our results showed a good correlation of the expression patterns of both the cell cycle (CDK4) and inflammatory (STAT3) markers studied and might be helpful for suggesting more selective agents in the therapeutic scenario of bladder cancer in the near future." (PMID 32102537, 2020). "Therefore, we applied the specific STAT3/5 inhibitors Stattic and SH-4-54 to 10 different bladder cancer cell lines, and Nifuroxazide in T24 and RT112 cell lines." (PMID 32046095, 2020). "The present study was aimed to explore the expression of CDk4 and STAT3 in bladder cancer tissues." (PMID 32102537, 2020). "On the other hand, molecular pathways, such as STAT3 participate in bladder cancer progression." (PMID 32992587, 2020). "Several studies have reported STAT3 as an important factor in the development of bladder cancer." (PMID 32102537, 2020). "Hence, in this study we investigated also the effects upon combining oncolytic adenovirus with STAT3/5 inhibitors in bladder cancer." (PMID 32046095, 2020). "Furthermore, we analysed the role of STAT3/5 in bladder cancer cell lines using 3 different STAT3/5 inhibitors Stattic, SH-4-54 and Nifuroxazide." (PMID 32046095, 2020). "Using a STAT3 transgenic mouse model, chemical induction of bladder cancer by N-butyl-N-(4-Hydroxybutyl) nitrosamine (BBN) directly resulted in the development of invasive carcinoma from carcinoma in situ, asserting the role of STAT3 in bladder cancer progression." (PMID 32046095, 2020). "In conclusion, the data presented here question the prognostic value of STAT3 in bladder cancer." (PMID 32046095, 2020). "STAT3 can individually promote the proliferation of bladder cancer cells, or it may be targeted by upstream mediators, such as Akt/ERK." (PMID 32992587, 2020). "Furthermore, through immunohistochemical studies of tissue microarrays, we assessed the expression of IGF2BP3 and phosphorylation of STAT3 in bladder cancer tissues." (PMID 33094561, 2020). "We also examined effects of STAT3/5 inhibitors on bladder cancer cell growth." (PMID 32046095, 2020). "Moreover, circRNA hsa_circ_0068871 regulates FGFR3 expression and activates STAT3 by targeting miR-181a-5p to promote bladder cancer progression, showing some of the important roles of circRNA in BC." (PMID 32460831, 2020). "ARRB2 also seems to regulate the transcription factor STAT3 in bladder cancer." (PMID 33297302, 2020).
bladder cancer (continued). "Similarly, high concentrations (40–80 μM) of chrysin were recently shown to inhibit p-STAT3 via the production of ROS in human bladder cancer cells." (PMID 31491838, 2019). "Moreover, it was noted that δ-T3 arrested the growth of human bladder cancer cells, induced apoptosis, and chemosensitization by inhibiting STAT3 pathway." (PMID 30717416, 2019). "Moreover, δ-T3, inhibited Src kinase, Janus kinase (JAK) 1, and JAK2, thus eventually downregulating STAT3 activation in bladder cancer cells." (PMID 30717416, 2019). "To investigate the effect of the CM iCAF on the activation of IL-6 signaling pathway in bladder cancer cells, we compared the expression levels of phosphorylated STAT3 (pSTAT3) and phosphorylated AKT (pAKT) in RT4 cells cultured with CM iCAF to control media (CM HF and CM HF + TGFß)." (PMID 30744595, 2019). "Furthermore, we found that IDO1 is a direct target of miR-153, which mediated miR-153 anti-tumor activity in bladder cancer via inactivating the IL6/STAT3/VEGF pathway." (PMID 31355138, 2019). "Although several studies have reported STAT3 as an important factor in the development of bladder cancer, the relation between STAT3 and UTUC progression remains unclear." (PMID 30091994, 2018). "Furthermore, knocking down of STAT3 enhanced the effect of THP on bladder cancer cells as well detected by MTT." (PMID 29512924, 2018). "While the influence of metformin on STAT3 in endometrial cancer is unknown, metformin has been shown to inhibit STAT3-mediated cell proliferation in breast, esophageal, and bladder cancers." (PMID 28114390, 2017). "Together with our own observations in bladder cancer samples, this data suggests that Blcap interaction with Stat3 may be a general event, and that this interaction has a regulatory role on Stat3 activity and presumably on cancer development." (PMID 29190807, 2017). "In conclusion, we have identified Blcap as a new Stat3 interactor in bladder cancer." (PMID 29190807, 2017). "Stat3 activation contributes to bladder cancer cell growth and survival." (PMID 29190997, 2017). "Finally, in Stat3-transgenic mice with BBN-induced bladder cancer, an early expansion of CK14+ stem cells has been observed." (PMID 27058422, 2016). "Thus, the down regulation of STAT3/cyclin D1 signaling can account for the cell cycle arrest in the G0/G1 stage and reduced G1/S phase transition in the bladder cancer cells treated with metformin." (PMID 26245871, 2015). "In consistence with the phenomenon, STAT3 phosphorylation was remarkably inhibited by metformin either in vitro or in vivo models of bladder cancers, accompanied by reduced capacity of migration and invasion of cancer cells in vitro and arrested progression of precancerous lesions." (PMID 26245871, 2015). "To further dissect the effects of δ-T3 on downstream signaling, we analyzed STAT3 signaling pathway, which is one of the major anti-apoptotic pathways, conferring the survival advantage and chemo-resistance of bladder cancer cells against various chemotherapeutic agents." (PMID 25849286, 2015). "Importantly, we have for the first time demonstrated that metformin can prevent precancerous progression through inhibiting STAT3-mediated signaling pathways in a MNU-induced orthotopic rat bladder cancer model." (PMID 26245871, 2015). "Moreover, it has been reported that activation of STAT3 is crucial for bladder cancer carcinogenesis, growth, survival and progression in vitro and in vivo." (PMID 26245871, 2015). "Moreover, qRT-PCR results revealed that three STAT3 direct target genes (bcl2, bclxl and mcl1) were downregulated at mRNA levels in both two bladder cancer cell lines, indicating that the reduction is mainly due to the transcriptional regulation." (PMID 25849286, 2015). "Furthermore, they demonstrated that the G-CSF/G-CSFR biological axis facilitated survival and growth of bladder cancer cells and stimulated STAT3-dependent survivin expression." (PMID 24885603, 2014).